SNORD115-23 (small nucleolar RNA, C/D box 115-23)
Synonyms: HBII-52-23
Gene: Small nucleolar RNA gene on chromosome 15 (25,211,796 to 25,211,877, forward strand). Ensembl gene ENSG00000201331.
Gene Ontology:
Biological process: RNA processing
Cellular component: nucleolus
Homologues: Orthologues: chimpanzee SNORD115 (100% identical), macaque SNORD115 (99% identical), dog SNORD115 (61% identical). Paralogues in human: SNORD115-11 (93% identical), SNORD115-29 (93% identical), SNORD115-36 (93% identical), SNORD115-43 (93% identical), SNORD115-6 (93% identical), SNORD115-10 (91% identical), SNORD115-12 (91% identical), SNORD115-16 (91% identical), SNORD115-22 (91% identical), SNORD115-26 (91% identical), SNORD115-34 (91% identical), SNORD115-39 (91% identical), and 37 more.